TMEM43 (transmembrane protein 43)
Diseases named in the same sentence as TMEM43 in open-access papers (continued):
Sharing a sentence is not in itself a finding about the gene and the disease.
pancreatic cancer (continued). "The GEPIA2 online tool employed to analyze the OS and recurrence‐free survival (RFS) of 30 genes revealed four genes, including CAV1, TMEM43, IQGAP1, and CDK1, that were significantly correlated with pancreatic cancer risk based on their differential expression between tumor and normal tissues." (PMID 40539383, 2025). "However, little is known concerning the biological function and molecular mechanisms of TMEM43 in pancreatic cancer." (PMID 35260078, 2022). "In addition, TMEM43 was silenced in SW1990 and Capan-2 cells, and these results also confirmed that the downregulation of TMEM43 significantly reduced pancreatic cancer cell growth and colony formation abilities." (PMID 35260078, 2022). "We also demonstrate that the suppression of TMEM43 could restrain pancreatic cancer growth, migration, and invasion in vitro and in vivo." (PMID 35260078, 2022). "The present study suggests that TMEM43 contributes to pancreatic cancer progression through the PRPF3/RAP2B/ERK axis, and might be a novel therapeutic target for pancreatic cancer." (PMID 35260078, 2022). "Moreover, we demonstrated that TMEM43 promoted pancreatic cancer progression by stabilizing PRPF3 and regulating the RAP2B/ERK axis." (PMID 35260078, 2022). "Taken together, these experimental data suggest that TMEM43 is upregulated in pancreatic cancer, and that TMEM43 may be an independent prognostic marker for pancreatic cancer patients." (PMID 35260078, 2022). "Overexpression of TMEM43 in pancreatic cancer cells was consistent with these results." (PMID 35260078, 2022). "The RAP2B/ERK axis transcription may be the downstream effect of TMEM43 in pancreatic cancer." (PMID 40725103, 2025). "Moreover, pancreatic cancer databases demonstrated that TMEM43 mRNA level was significantly positively associated with RAP2B mRNA expression level; we speculated that TMEM43 may regulate RAP2B expression through mediating RAP2B transcription level." (PMID 35260078, 2022). "Confocal immunofluorescence assays demonstrated that TMEM43 and PRPF3 colocalized in pancreatic cancer cell cytoplasm." (PMID 35260078, 2022). "The relationship of TMEM43 expression and disease-free survival (DFS) and overall survival (OS) were assessed in pancreatic cancer patients." (PMID 35260078, 2022). "TMEM43 mediates the RAP2B/ERK pathway by binding to and stabilizing PRPF3 to promote pancreatic cancer progression." (PMID 35260078, 2022). "Our study shows that the TMEM43/PRPF3/RAP2B/ERK axis plays a vital role in regulating cancer progression, and has a potential clinical application value for pancreatic cancer." (PMID 35260078, 2022). "To confirm that TMEM43 promotes pancreatic cancer progression by RAP2B, we overexpressed RAP2B in TMEM43-silenced SW1990 cells." (PMID 35260078, 2022). "TMEM43 promotes migration and invasion through the PRPF3/RAP2B/ERK axis in pancreatic cancer." (PMID 37367036, 2023). "To understand the molecular mechanisms of TMEM43 in pancreatic cancer, we identified differentially expressed proteins in the context of TMEM43 knockdown using the quantitative technique of label-free protein MS, and found that RAP2B is an important downstream target of TMEM43 in pancreatic cancer." (PMID 35260078, 2022). "The results found that patients with pancreatic cancer in TMA cohort 2 (p = 0.0354) with a high expression level of TMEM43 had worse OS, and patients in the cancer Genome Atlas (TCGA) database with a high expression level of TMEM43 had worse OS (p = 0.0092) and DFS (p = 0.0003)." (PMID 35260078, 2022). "However, the role of TMEM43 has not been reported in pancreatic cancer." (PMID 35260078, 2022).
Ventricular arrhythmia (4 papers, 2014 to 2021). "The pathophysiology by which TMEM43 mutation leads to altered cardiac IC disc proteins, conduction delay and ventricular arrhythmias of ARVC is still poorly understood and needs to be further investigated." (PMID 25343256, 2014). "Mutant TMEM43 was first described in families from Newfoundland (Canada) in 2008, as the cause of a fully penetrant aggressive disease with a high incidence of malignant ventricular arrhythmias, and was defined as ACM/ARVC type 5." (PMID 34930282, 2021). "Exercise has a similar negative impact on patients with the TMEM43 p.S358L variant, with recent publications showing athletic individuals had earlier onset of ventricular arrhythmias and a considerably worse survival free from appropriate ICD-therapy in follow-up." (PMID 34926342, 2021).
auditory neuropathy spectrum disorder (3 papers, 2021 to 2025). "Recently, a nonsense mutation in TMEM43, p.R372X, has been linked to an auditory neuropathy spectrum disorder (ANSD), indicating a TMEM43-related role in cochlea function." (PMID 41236655, 2025). "Perturbance of both TMEM43 and TASK-1 has shown to cause dysregulation of the cochlear K+ homeostasis via leak K+ channels and gap junction channels, leading to sensory dysfunction, auditory neuropathy, and hearing loss." (PMID 40725103, 2025). "TMEM43 is differentially expressed in different tissues, including the intercalated discs in cardiac myocytes, a likely contributor to the pathogenesis of various diseases such as arrhythmogenic cardiomyopathy, skeletal myopathies, cancers, and auditory neuropathy spectrum disorders." (PMID 40725103, 2025). "Herein, we present a deafness locus mapped to chromosome 3p25.1 and an auditory neuropathy spectrum disorder (ANSD) gene, TMEM43, mainly expressed in GLSs." (PMID 34050020, 2021).
dilated cardiomyopathy (3 papers, 2023 to 2025). Cardiomyopathy which is characterized by dilation and contractile dysfunction of the left and right ventricles. "Mutations in the LMNA gene are well-established causes of dilated cardiomyopathy: this interaction may also help explain the development of this phenotype in TMEM43 patients." (PMID 40869437, 2025).
glioblastoma (3 papers, 2018 to 2024). The most malignant astrocytic tumor (WHO grade IV). "Upregulation of TMEM43 in glioblastoma accelerates tumor survival and progression through the interaction of TMEM43 with CARD-containing MAGUK protein 3 (CARMA3) during EGFR-induced NF-κB activation." (PMID 38556553, 2024). "Furthermore, knocking out either CARMA3 or TMEM43 results in decreased growth and survival of human glioblastoma cells, both in vitro and in vivo." (PMID 30158935, 2018).
glioma (3 papers, 2022 to 2023). A benign or malignant brain and spinal cord tumor that arises from glial cells (astrocytes, oligodendrocytes, ependymal cells). "In vitro and in vivo assays showed that knockdown of TMEM43 inhibited glioma proliferation and metastasis." (PMID 35260078, 2022). "Previous studies have shown that TMEM43 expression levels are upregulated in high-grade glioma malignancy samples compared with normal control samples and low-grade glioma samples, and higher TMEM43 expression is associated with poorer survival outcomes." (PMID 35260078, 2022).
hearing loss (3 papers, 2021 to 2025). "Although it has been demonstrated in animal models that TMEM43-p.(Arg372Ter) mutation disrupts the function of gap junction proteins in cochlear GLSs, affects K+ cycling, and exhibits progressive hearing impairment, its pathogenic mechanism remains poorly characterized in humans." (PMID 39834515, 2024). "Transcriptome sequencing and bioinformatics analyses show that TMEM43 mutations may lead to hearing loss by affecting the PI3K-Akt signaling pathway and calcium signaling pathway resulting in decreased gap junction function, which may provide new ideas for drug screening and gene therapy." (PMID 39834515, 2024). "CpG cites in hearing loss candidate genes, KCNQ1, TMEM43, GSTM1, TCF25, and GSR, were found to be highly methylated in presbycusis patients as compared to the controls." (PMID 40428348, 2025). "This is consistent with our patient-derived iPSC model, where we observed little effect of TMEM43 mutation on GLS development at early stages, mirroring the late onset of hearing loss in both the mouse model and patients." (PMID 39834515, 2024). "Conversely, hearing loss has not been reported in TMEM43-p.(Ser358Leu) ARVC patients." (PMID 34050020, 2021). "Given that the ABR threshold of Tmem43+/KI was significantly higher than that of Tmem43+/+ at 16 kHz, the DPOAE results indicate a preserved OHC function in these frequency ranges and reflect the characteristics of nonhair cell–related ANSD rather than OHC-related hearing loss, in the Tmem43KI mice." (PMID 34050020, 2021).
Right ventricular cardiomyopathy (3 papers, 2014 to 2025). Right ventricular dysfunction (global or regional) with functional and morphological right ventricular abnormalities, with or without left ventricular disease. "Transmembrane protein 43 (TMEM43) plays an important role in maintaining the structure of the nuclear envelope, and mutations in TMEM43 are strongly associated with arrhythmogenic right ventricular cardiomyopathy." (PMID 34249924, 2021).
Sepsis (3 papers, 2022 to 2025). Sepsis is defined as life-threatening organ dysfunction caused by a dysregulated host response to infection. "In this study, we found that TMEM43 reduced the sepsis-induced ferroptosis as assessed by decreased ferric iron and lipid peroxidation." (PMID 36230956, 2022). "In the present study, we found that TMEM43 was down-regulated in sepsis-induced cardiac injury heart tissue and cardiomyocytes." (PMID 36230956, 2022). "Based on these findings, we concluded that TMEM43 protects against sepsis-induced cardiac injury via inhibiting ferroptosis in mice." (PMID 36230956, 2022). "The study demonstrated that TMEM43 protects against sepsis-induced cardiac damage by inhibiting ferroptosis in mice, which suggests the use of TMEM43 as a therapeutic target for preventing sepsis." (PMID 40725103, 2025). "Decreased TMEM43 resulted in a lower death rate and less cardiac injury during sepsis." (PMID 36230956, 2022). "By targeting ferroptosis in cardiomyocytes, TMEM43 may be a therapeutic strategy for preventing sepsis in the future." (PMID 36230956, 2022).
arrhythmogenic right ventricular dysplasia 5 (2 papers, 2012 to 2023). "In our study, TTN DCM type 1G, KCNQ1 LQTS type 1, MYBPC3 HCM type 4, and TMEM43 arrhythmogenic right ventricular dysplasia type 5 were the most frequent CVD, and MSH6 Lynch syndrome and PALB2 HBC were the most frequent CPC among ACMG SFs." (PMID 36635046, 2023).
channelopathy (2 papers, 2023 to 2024). Channelopathies are a group of diseases caused by the dysfunction of ion channel subunits or their interacting proteins. "The variants included three channelopathy-associated genes (RYR2, CACNA1C, and ANK2), three HCM- or DCM-associated genes (MYH7, LDB3, and PRKAG2), five ACM-related genes (PKP2, JUP, DSG2, DSP, and TMEM43), and two cardiac transcription factor genes (TBX5 and GATA4)." (PMID 39272661, 2024).
deafness (2 papers, 2021 to 2024). An inherited or acquired condition characterized by the complete loss of the ability to hear from one or both ears. "Our preliminary study identified a new deafness gene, TMEM43, whose mutation can lead to post-speech ANSD." (PMID 39834515, 2024). "In this study, we have identified a deafness locus, Chr 3: 13,165,401 to 14,502,000 (3p25.1), and a deafness gene, TMEM43, whose variation can cause ANSD post lingually." (PMID 34050020, 2021).
dementia (2 papers, 2021 to 2022). Loss of intellectual abilities interfering with an individual's social and occupational functions. "TOMM40/APOE locus linked to dementia (p = 2.40 × 10−4) and arthritis (p = 3.01 × 10−3), and TMEM43 was associated with Parkinson's disease (p = 0.045)." (PMID 33657282, 2021). "Moreover,mitochondrial complex I activity defects are consistently observed in the substantianigra and prefrontal cortex of patients with PD and dementia, suggesting that similar Tmem43-mediatedbiochemical and genetic triggers may exist for these two vital organs." (PMID 34766515, 2022).
Myocardial fibrosis (2 papers, 2022 to 2025). "Further studies are needed to characterize myocardial fibrosis in patients with TMEM43 mutations better, including the use of advanced post-processing software dedicated to scar identification." (PMID 40869437, 2025). "The phenotype in the TMEM43-p.S358L overexpressing zebrafish line was milder compared to the phenotype described in the transgenic mice, as reflected by the absence of myocardial fibrosis and electrical defects in adult zebrafish." (PMID 36076925, 2022).
neuroblastoma (2 papers, 2014 to 2018). Neuroblastoma (NB) is the most common solid, extracranial childhood tumor. "Luma, alternatively known as transmembrane protein 43 (TMEM43), is associated with the LINC complex and was initially identified with a proteomics screen for INM proteins in neuroblastoma cells." (PMID 29869195, 2018). "TMEM43 has been shown to localize to the endoplasmic reticulum and inner nuclear envelope (mouse neuroblastoma cells, COS-7, BHK, HeLa and other cell lines) and the GFP-tagged protein has also been shown to localize to the ER/inner nuclear envelope sites." (PMID 25343256, 2014).
cardiac hypertrophy (1 paper, 2025). "While downregulation of Tmem43 has been shown to play a critical role in cardiac hypertrophy via epithelial-to-mesenchymal transition in mouse models, TMEM43’s upregulation protects against lipopolysaccharide (LPS)-induced cardiac injury via inhibiting ferroptosis." (PMID 40725103, 2025).
colon cancer (1 paper, 2021). "Given that oxaliplatin is also a standard chemotherapeutic agent used in colon cancer treatment, we also examined the expression of molecular signature genes PIK3CA, SLC6A6, ASAP-1 and TMEM-43 in colon cancer cells resistant to this drug." (PMID 34571860, 2021). "To test whether PIK3CA, SLC6A6, TMEM-43, and ASAP-1 expression is driven by CLDN1 and CLDN7 expression, we analyzed these genes and proteins in CLDN1-overexpressing SW480 (SW480CLDN1) and CLDN7-knockdown DLD-1 (DLDCLDN7KD) colon cancer cell lines." (PMID 34571860, 2021).
Coronary artery disease (1 paper, 2021). "Coronary artery disease was excluded by coronary angiography or coronary computed tomographic angiography in all eight patients with TMEM43 mutations." (PMID 34930282, 2021).
diffuse large B-cell lymphoma (1 paper, 2022). "Surprisingly, by using the eRic database, we found that ENSR00000148786 expression was the highest in a B-cell malignancy, DLBC (diffuse large B-cell lymphoma), in which ENSR00000148786 also showed the highest correlation with TMEM43/LUMA (Rs=0.59, FDR= 8.4e-4)." (PMID 36741695, 2022).
embryonic carcinoma (1 paper, 2025). "However, the cell lines used in these studies were, i.e., derived from embryonic kidney cells (HEK cells) or embryonic carcinoma cells (P19 cells), which may not entirely reflect the cardiomyocyte-specific microenvironment or physiological in vivo condition in which TMEM43 naturally acts." (PMID 41236655, 2025).
fibrosis (1 paper, 2019). the formation of excess fibrous connective tissue in an organ or tissue in a reparative or reactive process. "Importantly, our studies suggest that TMEM43 S358L mutation contributes to cardiac fibrosis through NF-κB-TGFβ signal cascade during ARVD progress." (PMID 29980933, 2019).
laminopathies (1 paper, 2012). "We examined the effect of mutant TMEM43 on mRNA expression of four genes, LMO7, KCTD12, MBNL2 and RAP2A, located on chromosome 13, that have been shown to have abnormal expression in the setting of laminopathies with striated muscle dysfunction." (PMID 22458570, 2012).
macular degeneration (1 paper, 2024). Loss of vision in the central portion of the retina (macula), secondary to retinal degeneration. "Further examples include the contribution of TFAM on alkaline phosphatase heritability and its role in hepatocerebral mitochondrial DNA depletion syndrome, and the contribution of TMEM43 on HbA1c heritability and macular degeneration." (PMID 38336875, 2024).
Noonan syndrome with multiple lentigines (1 paper, 2023). A rare multisystem genetic disorder characterized by lentigines, hypertrophic cardiomyopathy, short stature, pectus deformity, and dysmorphic facial features. "This is also the case for 8/14 syndromic HCM (CACNA1C, FLNC, PRKAG2, PTPN11 (Noonan), PTPN11 (Noonan syndrome with multiple lentigines), RAF1, RIT1, TTR), 3/12 DCM (DES, TNNC1 and TNNT2), and 2/6 ARVC (JUP, TMEM43) gene-disease pairs." (PMID 37872640, 2023).
Parkinson disease (1 paper, 2021). A progressive degenerative disorder of the central nervous system characterized by loss of dopamine producing neurons in the substantia nigra and the presence of Lewy bodies in the substantia nigra and locus coeruleus. "The TMEM43 locus was associated with Parkinson's disease, AST, and UA." (PMID 33657282, 2021).
pterygium (1 paper, 2021). A wedge-shaped fibrovascular lesion arising from the bulbar conjunctiva and extending to the cornea. "The high expression of TMEM43 in pterygium, as in cancer, may act as a critical component in the EGFR signaling network to control cell survival, migration, and invasion." (PMID 34249924, 2021). "Using GEO databases, we also identified five hub genes (DSP, MXRA5, ARHGAP35, TMEM43, and OLFML2A) that were most correlated with the development of pterygium." (PMID 34249924, 2021). "After analyzing the differentially methylated m6A peaks and synchronously differentially expressed genes, we searched the Gene Expression Omnibus database and identified five genes related to the development of pterygium (DSP, MXRA5, ARHGAP35, TMEM43, and OLFML2A)." (PMID 34249924, 2021).
tumor (40 papers, 2006 to 2025). "Until now, only the pathological functions of TMEM43 have been implicated in arrhythmia and tumor progression." (PMID 34050020, 2021). "Higher TMEM43 gene expression was also found to correlate closely with brain tumor malignancy, while suppression inhibits tumor growth." (PMID 40725103, 2025). "The study also showed TMEM43 affected migration and invasion of cancer cells in vitro and tumor progression in vivo." (PMID 40725103, 2025). "TMEM43-overexpression facilitated tumor proliferation, migration, and invasion in MIAPaCa-2 cells in vitro." (PMID 35260078, 2022). "First, we examined TMEM43 mRNA levels in different tumor samples and corresponding control samples using the GEPIA database." (PMID 35260078, 2022). "First, knockdown of TMEM43 in Capan-2 and control cells were injected into the back of nude mice, and the results suggest that the tumor volume and weight were significantly decreased in TMEM43-silenced Capan-2 cells compared with control cells." (PMID 35260078, 2022). "Tumor development was also affected by TMEM43 expression levels in HCC." (PMID 40725103, 2025). "The downregulation of TMEM43 significantly reduced tumor cell proliferation and colony formation abilities in MIAPaCa-2 cells, whereas the upregulation of TMEM43 in TMEM43-silenced MIAPaCa-2 cells and significantly promoted cell proliferation and colony formation abilities." (PMID 35260078, 2022). "Moreover, in vitro and in vivo assays showed that knockdown of TMEM43 inhibited tumor growth, migration, and invasion in MIAPaCa-2, SW1990, and Capan-2 cells." (PMID 35260078, 2022). "Furthermore, transwell assays were used to explore the effect of TMEM43 on metastasis, which showed silencing TMEM43 obviously reduced tumor cell migration and invasion abilities in MIAPaCa-2, SW1990, and Capan-2 cells compared with the corresponding control cells." (PMID 35260078, 2022). "Moreover, tumor xenografts were also performed to confirm the functions of PRPF3 and RAP2B in vivo, and the results showed that the downregulation of TMEM43, PRPF3, and RAP2B obviously reduced tumor growth in MIAPaCa-2 cells." (PMID 35260078, 2022). "Moreover, many genes (PTN, SIAH2, FAM111B, TMEM43, FOSL2, TRIB1 and SPATA1) were hypomethylated regardless of tumor grade." (PMID 36850002, 2023).